BUD31 (BUD31 spliceosome associated protein)
Description:
Involved in the pre-mRNA splicing process. May play a role as regulator of AR transcriptional activity; may increase AR transcriptional activity.
Synonyms: EDG2; YCR063W; EDG-2; fSAP17; Cwc14; G10
Tractability: Small molecule: a structure with a bound ligand is known. PROTAC: ubiquitination databases record sites on it; its protein half-life has been measured.
Gene: Protein-coding gene on chromosome 7 (99,408,615 to 99,419,618, forward strand). Ensembl gene ENSG00000106245.
Subcellular location: Nucleus
Subcellular location (Human Protein Atlas): Nucleoplasm; Centrosome; Microtubules
Pathways (Reactome):
Disease: Dengue Virus-Host Interactions
Metabolism of RNA: mRNA Splicing - Major Pathway
Gene Ontology:
Molecular function: nuclear receptor binding; protein binding; transcription coactivator activity
Biological process: mRNA splicing, via spliceosome; positive regulation of DNA-templated transcription
Cellular component: chromatin; nucleoplasm; nucleus; post-mRNA release spliceosomal complex; post-spliceosomal complex; spliceosomal complex; U2-type catalytic step 1 spliceosome; U2-type catalytic step 2 spliceosome
Genetic constraint (gnomAD): Loss-of-function variants: 9 observed, 18.21 expected, observed/expected ratio (o/e) 0.49, 90% interval 0.3 to 0.86. The upper end of that interval is the gene's LOEUF score, 0.86, which puts it in group 3 of 6, group 1 being the genes least tolerant of losing a copy. Missense variants: 148 observed, 190.55 expected, observed/expected ratio (o/e) 0.78, 90% interval 0.68 to 0.89. Synonymous variants: 70 observed, 66.76 expected, observed/expected ratio (o/e) 1.05, 90% interval 0.86 to 1.28.
Homologues: Orthologues: chimpanzee BUD31 (100% identical), dog BUD31 (100% identical), macaque BUD31 (100% identical), mouse Bud31 (100% identical), pig BUD31 (100% identical), rabbit BUD31 (100% identical), rat Bud31 (100% identical), guinea pig BUD31 (99% identical), zebrafish bud31 (96% identical), tropical clawed frog bud31 (92% identical), Drosophila melanogaster l(1)10Bb (87% identical), Caenorhabditis elegans bud-31 (69% identical).
Diseases named in the same sentence as BUD31 in open-access papers:
BUD31 is named in the same sentence as 15 diseases in open-access papers, as found by Europe PMC text mining. Sharing a sentence is not in itself a finding about the gene and the disease. The quoted sentences say what the papers report.
ovarian carcinoma (4 papers, 2022 to 2025). A malignant neoplasm originating from the surface ovarian epithelium. "For example, as part of the spliceosome, BUD31 was shown to be upregulated in ovarian cancer, which is associated with a bad prognosis." (PMID 39212334, 2025). "Together, these results demonstrate that elevated expression of BUD31 is associated with worse prognosis in ovarian cancer patients." (PMID 36271053, 2022). "However, we observed that clinical data from patients diagnosed with testicular germ cell tumor, ovarian cancer, and lung squamous cell carcinoma indicated that low BUD31 expression was strongly associated with worse overall survival (OS)." (PMID 37047027, 2023). "The inhibition of BUD31 leads to splicing defects including substantial exon skipping and production of shortened isoforms, which can lead to the promotion of ovarian cancer." (PMID 39212334, 2025). "To further explore the function of BUD31 in ovarian cancer, we performed an EdU (5-ethynyl-2′-deoxyuridine) assay and found that BUD31 overexpression in HEYA8, A2780 and OVCAR3 cells significantly increased the number of EdU-positive cells." (PMID 36271053, 2022). "In this work, we report that overexpression of BUD31 predicts poor prognosis in ovarian cancer patients." (PMID 36271053, 2022). "Considering that high BUD31 expression predicts worse prognosis in ovarian cancer, we chose BUD31 for further investigation." (PMID 36271053, 2022). "Here we demonstrate that spliceosome component BUD31 is increased in ovarian cancer, and its higher expression predicts worse prognosis." (PMID 36271053, 2022). "Nevertheless, future study is needed to determine how BUD31 becomes overexpressed in ovarian cancer." (PMID 36271053, 2022). "Our findings reveal BUD31-regulated exon inclusion as a critical factor for ovarian cancer cell survival and cancer progression." (PMID 36271053, 2022). "To investigate the functional role of BUD31 in ovarian cancer, we established cell lines with BUD31 overexpression or BUD31 knockdown relative to the basal expression level of BUD31." (PMID 36271053, 2022). "Consistent with this, overexpression of BUD31 suppressed H2O2-induced ovarian cancer cell apoptosis." (PMID 36271053, 2022). "In order to identify functional target candidates involved in ovarian cancer progression, we integrated BUD31-bound genes and AS-related genes using CLIP-seq, RIP-seq and RNA-seq data." (PMID 36271053, 2022). "In conclusion, our study suggests that BUD31 acts as an oncogenic splicing factor and prognostic marker in ovarian cancer." (PMID 36271053, 2022). "We analyzed promoter region of BUD31 and found potential E2F1 binding sites on the BUD31 promoter region, indicating that E2F1 is potential transcriptional factor of BUD31 in ovarian cancer." (PMID 36271053, 2022). "We next investigated the functional role of BUD31 and found that BUD31 promoted the proliferation and survival of ovarian cancer cells and xenograft tumor growth." (PMID 36271053, 2022). "Here the authors show that splicing factor BUD31 enhances ovarian cancer progression by promoting exon inclusion in the anti-apoptotic BCL2 family member, BCL2L12." (PMID 36271053, 2022). "We next measured apoptosis in ovarian cancer cells upon BUD31 knockdown using Annexin V-PE/7-AAD staining and flow cytometry." (PMID 36271053, 2022). "Next, we measured the protein level of BCL2L12 in ovarian cancer cells with BUD31 knockdown or overexpression." (PMID 36271053, 2022). "Inhibition of BUD31 or the use of ASOs may provide potential therapeutic strategies for ovarian cancer." (PMID 36271053, 2022). "BUD31 overexpression drives an oncogenic splicing switch in BCL2L12 to produce full-length BCL2L12 that in turn confers cancer cells resistance to apoptosis promotes the proliferation of ovarian cancer cells." (PMID 36271053, 2022).
ovarian carcinoma (continued). "Additionally, growth curve and clonogenic assays showed that BUD31 overexpression significantly enhanced the proliferation of ovarian cancer cells, while silencing BUD31 had opposite effects." (PMID 36271053, 2022). "To investigate whether the regulation of BCL2L12 splicing by BUD31 mediate the oncogenic role of BUD31 in ovarian cancer, we first analyzed TCGA data and found that BCL2L12 was positively correlated with BUD31." (PMID 36271053, 2022). "Our study indicates that BUD31 is a critical oncogenic splicing factor that might act as a potential therapeutic target in ovarian cancer." (PMID 36271053, 2022). "Moreover, mouse xenograft experiments were conducted to assess the functional role of BUD31 in ovarian cancer tumorigenesis and progression." (PMID 36271053, 2022). "In the combined analysis of CLIP-seq, RIP-seq and RNA-seq data, we identified multiple potential direct binding targets (BCL2L12, RBCK1, E2F4, and CDK16) that may involve in BUD31-mediated ovarian cancer cell survival and proliferation." (PMID 36271053, 2022). "Importantly, BUD31 protein level was significantly increased in advanced ovarian cancer compared to early-stage patients." (PMID 36271053, 2022). "In addition, posttranscriptional or posttranslational regulation may be also involved in the regulation of BUD31 in ovarian cancer." (PMID 36271053, 2022). "We then conducted a RNAi screen of six splicing factors and found BUD31 and SF3B1 exhibited similar inhibitory effect on ovarian cancer cells." (PMID 36271053, 2022). "BUD31 stimulates the inclusion of exon 3 to generate full-length BCL2L12 and promotes ovarian cancer progression." (PMID 36271053, 2022). "To evaluate the clinical significance of BUD31 in SOC, we performed immunohistochemistry using a tissue microarray containing 149 ovarian cancer tissue samples and 73 fallopian tube tissues (FTs)." (PMID 36271053, 2022). "More importantly, we verify that BUD31 drives an oncogenic splicing switch of BCL2L12, which in turn promotes ovarian cancer progression." (PMID 36271053, 2022). "In addition, BUD31 was positively correlated with plenty of inclusion events, including BCL2L12 AS, in ovarian cancer based on PSI value profiles in the TCGA-Spliceseq database." (PMID 36271053, 2022). "Thus, our work supports the notion that BUD31 stimulates the inclusion of exon 3 to generate BCL2L12-L and promotes ovarian cancer progression." (PMID 36271053, 2022). "However, we failed to verify BUD31 is a direct target of MYC in ovarian cancer." (PMID 36271053, 2022).
breast carcinoma (3 papers, 2019 to 2022). "In breast cancer cells, BUD31 is required for cell migration." (PMID 36271053, 2022). "BUD31 is an MYC-synthetic lethal gene and is a potential therapeutic entry point for human breast cancers." (PMID 34986865, 2022).
breast tumors (1 paper, 2019). "The splicing factors PRPF4B and BUD31 and the transcription factor BPTF are essential for cancer cell migration, amplified in human primary breast tumors and associated with metastasis-free survival." (PMID 31278301, 2019).
cervical cancer (1 paper, 2015). A primary or metastatic malignant neoplasm involving the cervix. "BUD31 and PRSS2 belong to chromosomes 7, there are known changes of this chromosome in cervical cancer." (PMID 26388997, 2015).
male infertility (1 paper, 2025). The inability of the male to effect fertilization of an ovum after a specified period of unprotected intercourse. "Knockout of mice Bud31, the homolog of the human BUD31 gene (hBUD31), led to loss of spermatogonia and male infertility." (PMID 41227381, 2025).
prostate carcinoma (1 paper, 2023). A carcinoma that arises from epithelial cells of the prostate gland. "Overall, these results provide valuable insights into the potential diagnostic and prognostic significance of BUD31 in prostate cancer and highlight the importance of further investigation into its role in the disease." (PMID 37047027, 2023). "Interestingly, BUD31 has been implicated as a co-regulator of AR transcriptional activity in prostate cancer cell lines." (PMID 37047027, 2023). "Our in vitro results showed BUD31 knockdown promotes cell proliferation and migration of prostate cancer cells via activation of p-AKT and vimentin." (PMID 37047027, 2023). "Within our study, we aimed to investigate the expression of BUD31 protein in different stages of prostate cancer, including benign, incidental PCa, advanced PCa, and castrate-resistant PCa (CRPCa)." (PMID 37047027, 2023). "Our in vitro results supported these findings as the knockdown of BUD31 increased prostate cancer cell proliferation and migration." (PMID 37047027, 2023).
viral infection (1 paper, 2022). "Interestingly, we found that the ubiquitination of many host proteins that interact with SARS-CoV-2 was also changed after viral infection, such as ZDHHC5, BUD31, SCP2, ARL6IP4, and NUDCD2, which were reported to interact with the SARS-CoV-2 Spike protein." (PMID 36071039, 2022).
tumor (7 papers, 2020 to 2025). "Our in vitro studies revealed that BUD31 downregulation is associated with aggressive tumor cell behavior when compared to wildtype expression in PC3, PC3-ERG, and LNCaP cell lines." (PMID 37047027, 2023). "To conclude, our study acknowledges the role of BUD31 as a tumor suppressor as depicted by the results of our clinical and in vitro studies." (PMID 37047027, 2023). "Consistent with this, forced expression of BUD31 in ID8 cells induced a significant increase in tumor mass and volume in xenografts (n = 8)." (PMID 36271053, 2022). "We examined the expression level of BUD31 in the TCGA and Clinical Proteomic Tumor Analysis Consortium (CPTAC) data." (PMID 36271053, 2022). "Increased expression of BUD31, RIP4, and RPL39 have been previously correlated with disease malignancy and associated worse overall survival in patients with GBM, with in vitro overexpression of RPL39 associated with enhanced proliferation and migration of tumor cells." (PMID 39766155, 2024). "In addition, silencing BUD31 also decreased BCL2L12 expression in the xenograft tumor in vivo." (PMID 36271053, 2022). "Selective inhibition of CDK1/2 and the core component BUD31 of restriction enzymes can induce apoptosis of TNBC tumor cells overexpressing MYC, suggesting that TNBC, especially the BL1 and M subtypes, might benefit from CDK1/2 and restriction enzyme inhibitor treatment." (PMID 32517735, 2020). "Since the in silico and interspecific complementation analyses showed that the BUD31 gene was evolutionarily conserved from yeast to humans and retained its functional homology, these data may contribute to a better understanding development of human tumor cells." (PMID 41227381, 2025). "Furthermore, a limitation of this study involves the lack of heterogeneity found in the in vitro studies and, hence, why future studies may be necessary to elaborate on the nature of BUD31 expression in different molecular signatures across a variety of different tumor cell types." (PMID 37047027, 2023). "BUD31 knockdown in HEYA8 cells significantly reduced the number and size of tumor nodes in the abdominal cavity." (PMID 36271053, 2022).
cancer (6 papers, 2019 to 2025). A tumor composed of atypical neoplastic, often pleomorphic cells that invade other tissues. "Metastasis is a key hallmark of cancer progression and understanding the role of BUD31 in this process is of great importance." (PMID 37047027, 2023). "The human BUD31 protein proved to be an important co-activator of the androgen receptor’s transcriptional activity, while other studies revealed that deletion or overexpression of this gene has been associated with various types of cancers." (PMID 41227381, 2025). "The human BUD31 gene has been associated with various processes including cancer." (PMID 41227381, 2025). "This function was also found in PCa as studies in the field found that the upregulation of vimentin led to increased cancer cell invasiveness; this trend was also observed in our study’s in vitro experiments when BUD31 was knocked down." (PMID 37047027, 2023). "Nonetheless, the alternative splicing regulation and clinical significance of BUD31 in cancer remain poorly understood." (PMID 36271053, 2022). "Additionally, bioinformatic analysis and GSEA revealed that BUD31 increased processes related to cancer cell migration and proliferation." (PMID 37047027, 2023). "However, we were able to correlate low BUD31 expression to worse overall and return-free survival in multiple other cancer subtypes." (PMID 37047027, 2023). "In our study, our initial focus was to examine whether low BUD31 expression was prevalent in other types of cancers." (PMID 37047027, 2023). "Pan-cancer analysis revealed that BUD31 is overexpressed in various cancer types." (PMID 36271053, 2022). "We found that BUD31 was commonly overexpressed in SOC and that a high level of BUD31 was associated with poor prognosis, and pan-cancer analysis showed that BUD31 was overexpressed in various cancer types." (PMID 36271053, 2022). "BUD31 is a core splicing factor essential for spliceosome assembly, catalytic activity and associates with multiple spliceosome sub-complexes and has shown to be a MYC target in MYC-driven cancer cells." (PMID 31278301, 2019). "However, the BUD31-regulated cancer-specific splicing events and its binding motif remain largely unknown." (PMID 36271053, 2022). "Previous studies showed similar effects for the splicing factors BUD31 and SRSF1, the knockdown of which leads to inhibited proliferation and increased apoptosis in other cancer types." (PMID 39212334, 2025).
BUD31 also shares sentences with these, for which no sentence is quoted: endometrial cancer (1 paper); leukemia (1); lung squamous cell carcinoma (1); prostate adenocarcinoma (1); testicular germ cell tumor (1); thyroid carcinoma (1).